ZNF750 (zinc finger protein 750)
Diseases named in the same sentence as ZNF750 in open-access papers (continued):
Sharing a sentence is not in itself a finding about the gene and the disease.
cancer (18 papers, 2017 to 2024). A tumor composed of atypical neoplastic, often pleomorphic cells that invade other tissues. "Another question that still needs to be addressed is which molecular mechanism underlies the loss of ZNF750 expression in cancer." (PMID 37047491, 2023). "To explore the potential molecular mechanism underlying decreased ZNF750 induced angiogenesis and metastasis, we performed PCR array in ZNF750 knockdown cells using the kit of Cancer Pathway Finder PCR Array and validated by qRT-PCR." (PMID 32341351, 2020). "In conclusion, at this stage it is very difficult to draw clear conclusions regarding the molecular mechanisms involved in the regulation of ZNF750 expression in cancer." (PMID 37047491, 2023). "In conclusion, it is emerging that ZNF750 can potentially act as a prognostic biomarker in cancer and most likely be used to predict the formation of metastasis." (PMID 37047491, 2023). "Mechanistically, ZNF750 suppresses the expression of some cancer-related genes such as angiogenin, VEGF, RGS5, CD105, ITGA5, ITGB1, and CD44." (PMID 34288812, 2021). "The validation of decreased FOSL1 (Fos-like antigen 1) and increased EMP1 was further define the potential anti-cancer effect of ZNF750." (PMID 29416636, 2018). "The signaling pathway regulated by ZNF750 support the role of ZNF750 in regulating proliferation, apoptosis, inflammation and oxidative response, unveil ZNF750 as a new the potential anti-cancer gene for OSCC." (PMID 29416636, 2018). "Through TCGA pan-cancer analysis encompassing 33 cancer types, we unveiled significant correlations between immune checkpoint genes, chemokines, chemokine receptors, immune-stimulating and immune-inhibitory genes, and immunity scores with ZNF750 or TNC." (PMID 38711034, 2024). "And, ZNF750 expression positively correlated with the KRT5 level in most cancer types." (PMID 37365152, 2023). "The human zinc finger (C2H2-type) protein ZNF750 is a transcription factor regulated by p63 that plays a critical role in epithelial tissues homoeostasis, as well as being involved in the pathogenesis of cancer." (PMID 33298895, 2020). "ZNF750 is another member of the family that is involved in cancer." (PMID 29152378, 2017). "This suggests that ZNF750 may be a promising target for sensitizing cancer cells to therapy." (PMID 34288812, 2021). "Therefore, the decrease or inactivation of ZNF750 may lead SNAI1 to be free from the expression inhibition and trigger the EMT process associated with increased cancer invasion and metastasis." (PMID 32042337, 2020). "In agreement with previous reports on various types of human cancers, DANCR may also act as an oncogene in ESCC progression, supporting that DANCR may offer a potential therapeutic target for those ESCC patients harboring mutations of ZNF750." (PMID 32341351, 2020). "Therefore, it is tempting to hypothesize that ZNF750 sensitizes cancer cells to chemotherapy by repressing the expression of RAC1." (PMID 33298895, 2020). "However, the functional mechanism of ZNF750 in cancer remains obscure." (PMID 30518868, 2018). "Indicating the ZNF750 could induce the cell cycle arrest to inhibit the cancer cell proliferation." (PMID 29416636, 2018). "Therefore, the abnormal expression of ZNF750 in oral keratinocyte may lead to imbalance of cell proliferation and development to malignant tumor." (PMID 29416636, 2018). "We further investigated why the ZNF750-TNC axis affects the malignant phenotypes and immunogenicity of cancer cells." (PMID 38711034, 2024). "Furthermore, pancancer analysis of 33 cancer types in TCGA revealed that TRIM29 expression positively correlated with ZNF750 and KRT5 levels in most cancer types." (PMID 37365152, 2023). "Furthermore, our study sheds light on the role of the ZNF750-TNC axis in the regulation of DNA damage repair, which may alter the immunogenicity of cancer cells." (PMID 38711034, 2024).
cancer (continued). "In addition, we also found that ZNF750 could directly bind the promoter and promote the expression of KRT5, dysregulation of which could promote cancer invasion and metastasis." (PMID 37365152, 2023). "Compared to Del-c1 and c3, the majority of cancer genes were deleted by DEL-c2, such as CDKN2A (207/528), FHIT (133/528), KDM6A (42/528), RB1 (27/528), FAT1 (23/528), NFE2L2 (13/528), ERBB4 (20/528), CUL3 (11/528), PTEN (9/528), ZNF750 (13/528) and NOTCH1 (8/528)." (PMID 36272974, 2022).
adenocarcinoma (2 papers, 2020 to 2023). A common cancer characterized by the presence of malignant glandular cells. "The data from TCGA also showed the inactivating mutation rate of ZNF750 in LUSC was much higher than that in the corresponding adenocarcinoma." (PMID 32042337, 2020).
ZNF750 also shares sentences with these, for which no sentence is quoted: head and neck squamous cell carcinoma (3 papers); Arthritis (1); bladder cancer (1); cardiac hypertrophy (1); cervical squamous cell carcinoma (1); colorectal cancer (1); epidermolytic hyperkeratosis (1); genetic skin diseases (1); Harlequin ichthyosis (1); head and neck cancer (1); ichthyosis vulgaris (1); lung adenocarcinoma (1); pancreatic cancer (1); Psoriasiform dermatitis (1); psoriatic arthritis (1); sebaceous carcinoma (1).